ABCD2 (ATP binding cassette subfamily D member 2)
Description:
ATP-dependent transporter of the ATP-binding cassette (ABC) family involved in the transport of very long chain fatty acid (VLCFA)- CoA from the cytosol to the peroxisome lumen. Thus, may play a role in regulation of VLCFAs and energy metabolism namely, in the degradation and biosynthesis of fatty acids by beta-oxidation.
Synonyms: hALDR; ALDL1; ALDR; ALDRP; ABC39
Tractability: Antibody: UniProt predicts a signal peptide or a membrane-spanning region. PROTAC: ubiquitination databases record sites on it.
Gene: Protein-coding gene on chromosome 12 (39,550,033 to 39,619,803, reverse strand). Ensembl gene ENSG00000173208.
Subcellular location: Peroxisome membrane
Pathways (Reactome):
Protein localization: Class I peroxisomal membrane protein import
Transport of small molecules: ABC transporters in lipid homeostasis
Gene Ontology:
Molecular function: ATP hydrolysis activity; ATPase-coupled transmembrane transporter activity; fatty acyl-CoA hydrolase activity; protein binding; protein homodimerization activity; very long-chain fatty acyl-CoA hydrolase activity; ATP binding; long-chain fatty acid transmembrane transporter activity; protein heterodimerization activity; ABC-type transporter activity
Biological process: fatty acid beta-oxidation; positive regulation of fatty acid beta-oxidation; very long-chain fatty acid catabolic process; very long-chain fatty acid metabolic process; long-chain fatty acid import into peroxisome; myelin maintenance; negative regulation of cytokine production involved in inflammatory response; negative regulation of reactive oxygen species biosynthetic process; neuron projection maintenance; peroxisome organization; positive regulation of unsaturated fatty acid biosynthetic process; fatty acid biosynthetic process; positive regulation of lipid metabolic process; regulation of fatty acid metabolic process; transmembrane transport
Cellular component: peroxisomal membrane; peroxisome; cytosol; membrane
Genetic constraint (gnomAD): Loss-of-function variants: 31 observed, 58.63 expected, observed/expected ratio (o/e) 0.53, 90% interval 0.4 to 0.71. The upper end of that interval is the gene's LOEUF score, 0.71, which puts it in group 2 of 6, group 1 being the genes least tolerant of losing a copy. Missense variants: 653 observed, 836.27 expected, observed/expected ratio (o/e) 0.78, 90% interval 0.73 to 0.83. Synonymous variants: 281 observed, 296.22 expected, observed/expected ratio (o/e) 0.95, 90% interval 0.86 to 1.05.
Homologues: Orthologues: chimpanzee ABCD2 (99% identical), macaque ABCD2 (99% identical), dog ABCD2 (96% identical), pig ABCD2 (96% identical), mouse Abcd2 (94% identical), guinea pig ABCD2 (94% identical), rat Abcd2 (93% identical), rabbit ABCD2 (83% identical), tropical clawed frog abcd2 (80% identical), Caenorhabditis elegans pmp-4 (54% identical), zebrafish abcd2 (48% identical), and 1 more. Paralogues in human: ABCD3 (36% identical), ABCD4 (23% identical).
Diseases named in the same sentence as ABCD2 in open-access papers:
ABCD2 is named in the same sentence as 54 diseases in open-access papers, as found by Europe PMC text mining. Sharing a sentence is not in itself a finding about the gene and the disease. The quoted sentences say what the papers report.
Stroke (35 papers, 2011 to 2025). Sudden impairment of blood flow to a part of the brain due to occlusion or rupture of an artery to the brain. "Recent study revealed that tissue-positive events with low ABCD2 scores and tissue-negative events with high ABCD2 scores had similar stroke risks, and ABCD2 score had a validity in predicting stroke risk in tissue-positive TIA27." (PMID 37634045, 2023). "ABCD2 is an easily accessible, elementary, universal prediction tool for short-term risk for stroke (days-to-months), aimed to guide management of patients with a transient ischemic attack (TIA) in primary care or emergency settings." (PMID 35494231, 2022). "We aimed to evaluate the ABCD3-I score and compare it with the ABCD2 score in short- (1 week) and long-term (3 months; 1 year) stroke risk prediction in our post-TIA stroke risk study, MIDNOR TIA." (PMID 33708373, 2021). "When comparing low- to high-risk ABCD2 categories, the rate of stroke increased from 0.9% to 1.0% within 1 week, 1.9% to 4.1% within 3 months, and 2.8% to 6.6% and within 1 year." (PMID 33708373, 2021). "Due to the low numbers of stroke, the study did not have sufficient power to detect significant differences in stroke risk between patients with high and low ABCD2 score." (PMID 30606138, 2019). "A few risk scores have been developed to identify high-risk TIA or minor stroke patients, for instance, the ABCD2 score, which has been commonly used in research and in clinical practice." (PMID 30881336, 2019). "In fact, approximately 20% of patients with ABCD2 <4 harbor either an atherosclerotic or a cardiogenic source of stroke and 3-month stroke risk comparable to those with scores >437." (PMID 29263784, 2017). "At one year following stroke, the ABCD2 rule is more useful at ruling out stroke in those classified as low risk using all three cut-points, with a greater summary estimates of sensitivity than specificity." (PMID 24886654, 2014). "In a multivariable model which included ABCD2 score, aPS/PT IgG remained associated with stroke or death (OR 15.7, 95% CI 2.0–125.6, p = 0.009)." (PMID 23060855, 2012). "ABCD or ABCD2 scores (>4) = have a substantially higher early 7-day risk of stroke, which ranges between 5.6 and 23.8 percent." (PMID 22389822, 2011). "In the largest validation study involving 4,800 TIA cases it was shown that the ABCD2 score was highly predictive of subsequent stroke risk." (PMID 22389822, 2011). "All these studies consistently indicate that patients classified with ABCD or ABCD2 scores higher than 4 have a substantially higher risk of early stroke." (PMID 22389822, 2011). "Our comprehensive paper suggested that all scores have and equivalent prognostic value in predicting short-term risk of stroke; however, the ABCD2 score is being predominantly used at most centers." (PMID 22389822, 2011). "By identifying BBB dysfunction, HARM offers an alternative pathway to predict stroke recurrence, particularly in embolic stroke mechanisms, and may enhance risk stratification beyond ABCD2 and DWI." (PMID 40002503, 2025). "Previous studies classified TIA according to typical clinical symptoms and reported that ABCD2 score could predict the risk of stroke after AC-TIA, but might have limitation for PC-TIA4." (PMID 37634045, 2023). "These dissimilarities indicated that ABCD2 score could have different abilities in predicting the risk of recurrent stroke in AC-TIA and PC-TIA." (PMID 37634045, 2023). "Previous study reported that ABCD2 score could predict the stroke risk after AC-TIA but might have limitation for PC-TIA." (PMID 37634045, 2023). "ABCD2 score could predict the short-term risk of recurrent stroke after AC-TSI and PC-TSI, and had similar predictive abilities for AC-TSI and PC-TSI." (PMID 37634045, 2023). "Lastly, we investigate whether increased stroke risk, as assessed by the ABCD2, is associated with reduced cognition." (PMID 32373041, 2020).
Stroke (continued). "Increased stroke risk (i.e., ABCD2 score) was also associated with reduced cognition, suggesting that it may be helpful in signaling the need for further cognitive evaluation and intervention post-event." (PMID 32373041, 2020). "Our results can still indicate that the ABCD2 score may be less applicable to discriminate between high and low stroke risk groups in populations with a low risk of stroke after TIA." (PMID 30606138, 2019). "However a new and interesting finding was that patients with a high ABCD2 score also had a low risk of stroke." (PMID 30606138, 2019). "However, there is a need for consensus in relation to the identification of individuals at high risk of subsequent stroke as the various cut-points of ABCD2 score used to categorise stroke risk have considerable economic and management implications." (PMID 24886654, 2014). "However, the previous study reported that ABCD2 score could predict the short-term risk of stroke after AC-TIA, but might have limitation for PC-TIA4." (PMID 37634045, 2023). "Therefore, we divided TSI patients into anterior circulation TSI (AC-TSI) and posterior circulation TSI (PC-TSI) according to the location of infarction in this study, and we aimed to assess the value of the ABCD2 score for predicting stroke risk after either AC-TSI or PC-TSI." (PMID 37634045, 2023). "However, the evidence supporting ABCD2 score for predicting stroke risk remains inconclusive." (PMID 28638365, 2017). "Considering the best cut-off of each score, only ABCD2 > 3 showed a sensitivity of 100% only in the prediction of stroke within 7 days." (PMID 35986834, 2022). "Recently, a combination of ABCD2 ≥ 4 and a central pattern of nystagmus has been shown to yield higher sensitivity than the ABCD2 score alone for identifying stroke." (PMID 35250839, 2022). "Evaluating the cut-offs of each score for each clinical outcome, only ABCD2 (with a score > 3) showed a sensitivity of 100% for stroke within 7 days, with an NPV of 100% (95% CI 97–100%)." (PMID 35986834, 2022). "This suggests that ABCD2 can be useful in excluding patients having a stroke in the short term (7 days)." (PMID 35986834, 2022). "Interpreting our data, we noticed that patients with a low ABCD2 score and a low ABCD3-I score even more so had an extremely low risk of stroke after TIA." (PMID 33708373, 2021). "In the last two decades, clinical scores have been established to estimate the stroke risk following a TIA, with the ABCD2 and the ABCD3-I scores being the best validated ones." (PMID 33708373, 2021). "The AUC values of ABCD3-I were higher than those of ABCD2 at each time point, but the difference only reached statistical significance for stroke recurrence at 1 week." (PMID 33708373, 2021). "In terms of median accuracy and area-under-the-curve (AUC), all machine-learning classifiers outperformed the detection rate of stroke as indicated by ABCD2." (PMID 32529578, 2020). "In a prospective cohort of 180 patients with TIA or minor stroke to predict recurrent stroke and functional impairment at 90 days, the area under the curve was higher for ABCD2+MRI (0.88 vs. 0.78, P = 0.01)." (PMID 31781015, 2019). "ABCDE+ was validated in a cohort of 150 patients with TIA with the superior area under the curve for ABCDE+ compared with ABCD2 for predicting stroke (0.64 vs. 0.60) and for predicting death (0.62 vs. 0.56)." (PMID 31781015, 2019). "Only one study has analyzed the ability of ABCD2 to predict recurrent strokes (unspecified if ischemic or ipsilateral) among patients with symptomatic carotid stenosis, but this study was limited by a small sample size (n = 29 and 2 strokes)." (PMID 25433667, 2014). "In the same study, ABCD2 score, large artery atherosclerosis, and positive DWI findings were independently associated with an increased 7-day and 3-month risk of stroke." (PMID 22389822, 2011).
Stroke (continued). "In a pooled analysis of 6 cohorts, the ABCD2, ABCD and California scores have similar accuracy predicted for 2-, 7-, or 90-day stroke risk (AUROC curve .62–.83 versus .62–.81 versus .60–.79)." (PMID 22389822, 2011). "Another study showed that ABCD or ABCD2 Scores of >2 predicted raised stroke risks at 1, 5, and 10 years." (PMID 22389822, 2011). "In addition, the ABCD2 score elevated along with the increased expression of KCNQ1OT1 in TIA patients who suffered recurrent stroke (R2 = 0.2577, p < 0.05)." (PMID 36278219, 2022). "There are some studies that indicated that higher ABCD2 scores may predict the diagnosis of a minor stroke, which may contribute to its predictive usefulness." (PMID 32552700, 2020). "In comparison, ABCD2 detected stroke with a lower accuracy of 45.4%, at a ROC-AUC of 0.58." (PMID 32529578, 2020). "Third, we did not assess the risk factors of the recurrence of TIA or stroke, lack of subgroup analysis such as low, medium, and high risk according to ABCD2/ABCD3/ABCD3-I scores." (PMID 31379718, 2019). "ABCD2 and/or atrial fibrillation are not good scoring candidates for assessing the risk of recurrent stroke within first 90 days." (PMID 27642521, 2016). "In other words, ABCD2 and/or atrial fibrillation are not good scoring candidates for assessing the risk of recurrent stroke within first 90 days." (PMID 27642521, 2016). "The reason why ABCD2 score could not predict stroke risk after PC-TIA might be that previous studies differentiate AC-TIA and PC-TIA according to typical clinical symptoms." (PMID 37634045, 2023). "We hypothesized that integrated analyses of symptomatic carotid stenosis patients at increased stroke risk stratified by clinical scores, CAR and ABCD2, with transcriptomic and clinical data could improve identification of molecular pathways and targets for instability." (PMID 35494231, 2022). "Furthermore, adjustment of the serum copeptin level with the ABCD2 score could improve this scoring system’s prognostic value for the prediction of stroke." (PMID 35207321, 2022). "Moreover, those with a ABCD2 score <4 and ≥4 could have similar risks of recurrent stroke at 3 months." (PMID 30881336, 2019). "Our finding is similar to the results of recent studies, which showed that the ABCD2 score might not be a reliable tool to define a higher risk of the recurrent stroke." (PMID 30972019, 2019). "The objective is to compare the accuracy of ABCD2, ABCD2-I, and OTTAWA scores in the prediction of a stroke at 7, 90 days, and 1 year in patients presenting with TIA." (PMID 35986834, 2022). "In general, ABCD2 score was considered an important method for the diagnosis of TIA and the prevention of stroke, but its accuracy in predicting CI in TIA remains limited." (PMID 35261213, 2022). "In a validation cohort of 1,232 patients, ABCD3 and ABCD3-I predicted early stroke at 7, 28, and 90 days but the performance of ABCD3 was similar to ABCD2 in this validation cohort." (PMID 31781015, 2019). "ABCD2, ABCD2-I, and OTTAWA scores were significantly higher in patients who developed a stroke." (PMID 35986834, 2022). "As for the stroke risk prediction score, ABCD3, but not ABCD2, was significantly associated with seeking medical attention." (PMID 33178128, 2020). "A multicenter cohort study indicated that tissue-positive events with low ABCD2 scores and tissue-negative events with high ABCD2 scores had similar stroke risks, especially after a 90-day follow-up." (PMID 26394400, 2015). "In a study to assess the performance of ABCD2 score in TIA patients subcategorized as tissue-positive or tissue-negative on DWI or CT imaging, it was found that positive tissue patients with low ABCD2 and tissue negative patients with high ABCD2 had similar stroke risks." (PMID 31781015, 2019).
Stroke (continued). "Our results are also similar to those reported in a systematic review of the discriminative accuracy of the ABCD2 at seven days [AUC 0 · 72 (95% CI 0 · 63-0 · 82)], suggesting that the rule has reasonable ability to correctly distinguish patients with and without stroke at three years." (PMID 24886654, 2014). "ABCD2 performed with an accuracy of 37.7 (ROC-AUC of 0.59) for stroke with AVS, and 38.6% (ROC-AUC of 0.62) for stroke without AVS." (PMID 32529578, 2020).
diabetes (6 papers, 2010 to 2022). "There were significant group differences in sex (p < 0.001), ABCD2 categories (p < 0.001), number of vascular risk factors (p < 0.001), and prevalence of all vascular risk factors excluding hyperlipidemia and diabetes (all p < 0.033)." (PMID 32373041, 2020). "Of the other single ABCD2 factors, only diabetes was significantly associated with new cardiovascular ischemic events in univariate analysis (HR 4.94, 95% CI 1.41 to 17.30, P = 0.01)." (PMID 20565966, 2010).
transient ischemic attack (5 papers, 2010 to 2022). A brief attack (from a few minutes to an hour) of cerebral dysfunction of vascular origin, with no persistent neurological deficit. "Both of these factors have been included in the ABCD2 Transient Ischemic attack (TIA) prognostic rule to predict early recurrent stroke." (PMID 21513559, 2011).
X-linked adrenoleukodystrophy (5 papers, 2013 to 2023). X-linked adrenoleukodystrophy (X-ALD) is a peroxisomal disorder resulting in cerebral demyelination, axonal dysfunction in the spinal cord leading to spastic paraplegia, adrenal insufficiency and in some cases testicular insufficiency. "Overexpression of ABCD2 alone prevented oxidative lesions to proteins in a mouse X-linked Adrenoleukodystrophy model." (PMID 32518714, 2020).
hepatocellular carcinoma (4 papers, 2013 to 2020). A malignant tumor that arises from hepatocytes. "Moreover, real-time PCR analysis revealed that β-catenin and TCF-4 increased mRNA levels of ABCD2 in both a hepatocellular carcinoma cell line and primary fibroblasts from an X-ALD patient." (PMID 23437103, 2013). "In the inflammation category, Lgals1 (Galectin-1), an important immune response modulator and biomarker for hepatocellular carcinoma (HCC) was also markedly increased in SO-HFD but not HFD, as were Abcd2, Cd63, Ly6d and Ubd." (PMID 26200659, 2015).
atrial fibrillation (3 papers, 2011 to 2019). A disorder characterized by an electrocardiographic finding of a supraventricular arrhythmia characterized by the replacement of consistent P waves by rapid oscillations or fibrillatory waves that vary in size, shape and timing and are accompanied by an irregular ventricular response. "However, as shown in earlier studies, patients with low ABCD2 score may have underlying severe pathology, like atrial fibrillation and internal carotid stenosis, which underscores benefit from rapid diagnostic evaluation regardless of risk score." (PMID 30606138, 2019). "Interestingly, the relevance of some other risk profiles such as atrial fibrillation with increased risk for recurrent brain stroke has been proposed, and thus it seems that adding this factor to common scoring systems such as ABCD2 can increase its prognostic value for these patients." (PMID 27642521, 2016). "Second, we also showed that even adding the parameter of atrial fibrillation could not improve the predicting value of ABCD2." (PMID 27642521, 2016).